IL6 (interleukin 6)
Diseases named in the same sentence as IL6 in open-access papers (continued):
Sharing a sentence is not in itself a finding about the gene and the disease.
asthma (continued). "Our data revealed that airway inflammatory response in severe asthma group was significantly increased, which was characterized by dominated neutrophils accompanied by markedly elevated IL-17A and IL-6, and these inflammatory metrics were consistent with severe asthma and steroid-resistant asthma." (PMID 26974537, 2016). "IL-6 in induced sputum of patients evolving asthma is increased and correlated with FEV140." (PMID 27087690, 2016). "The maternal CES-D scores were positively associated with IL-6 expression in children with asthma but not in those without allergic diseases." (PMID 26819847, 2016). "IL-6 may affect asthma development, for example, by stimulating neutrophil recruitment and T helper cell differentiation into Th2 or Th17 cells (the latter in the presence of TGF-β) or by stimulating IL-13 production by T helper cells." (PMID 27212806, 2016). "Additionally, there were significant interactions between JPSS score and the presence of asthma and allergic rhinitis regarding IL-6 (P = 0.017) and IL-8 (P = 0.034) expressions." (PMID 26819847, 2016). "Pro-inflammatory cytokines, such as TNF-α, IL-1β, and IL-6, are involved in both asthma and COPD and may play a role in amplifying inflammation and thus determining disease severity." (PMID 27812337, 2016). "When macrophages are deficient in gal-3 there is increased responses to LPS, reduced bacterial replication and increased expression of IL-1β, TLR2 and IL-6, which are similar observations to those we have previously reported in patients with the neutrophilic subtype of asthma and COPD." (PMID 25616863, 2015). "Interestingly, both p38α MAPK and IKK-2 activities are elevated in severe asthma, as are a number of H3-Pser10-regulated genes including IL-6, CCL-2 and CXCL-8." (PMID 25905622, 2015). "However, the exact role of IL-6 in asthma pathology is not fully understood and has to be further elucidated." (PMID 25849971, 2015). "Compared to healthy control subjects, patients with asthma had significantly more percentages of eosinophils and neutrophils, IL-1RA, IL-1α, IL-1β, IL-2Rα, IL-5, IL-6, IL-7, IL-8, G-CSF, GROα (CXCL1), MIP-1β (CCL4), MIG (CXCL9), RANTES (CCL5) and TRAIL in their BAL fluids." (PMID 26011707, 2015). "Th2-related cytokines (IL-5, IL-6, and IL-13) can contribute to the induction of asthma." (PMID 25658604, 2015). "In a murine model of agricultural (occupational) asthma, repetitive nasal instillation of organic dust extract derived from animal farming operations increased IL-17, IL-1β and IL-6 protein concentrations in lung homogenates as well as induced a neutrophilic infiltrate in the lungs." (PMID 26561853, 2015). "In addition, IL-27 is a member of the IL-6/IL-12 family of cytokines, and rare variants in IL12RB1 have been previously implicated in asthma, suggesting that this family of cytokines and receptors should be the target of additional studies." (PMID 25116239, 2014). "Regardless of these limitations, this network of microRNAs may potentially be used as a therapy to balance the levels of IL-6 and IL-8 in asthma with a low off-target effect." (PMID 25360780, 2014). "Cytokines such as TNFα, IL6 secreted by the adipocytes are important mediators of asthma." (PMID 24409194, 2014). "Our data suggest that deficiency of microRNAs may contribute to the exacerbated expression of both IL-6 and IL-8 in asthma." (PMID 25360780, 2014). "IL-6 is a cytokine with multiple biological roles and traditionally considered a pro-inflammatory marker as its levels are often detected to be increased in inflammatory diseases such as asthma." (PMID 24237854, 2013). "In severe asthma, allergen sensitization and challenge increased Il6, Il5, and Il10 expression." (PMID 23781124, 2013). "Finally, a clinically-proven anti-IgE monoclonal antibody Omalizumab abrogated the IgE-induced mediators of asthma relevance such as IL-4, IL-6, IL-8, and TNF." (PMID 24499258, 2013).
asthma (continued). "In severe asthma, Tbet expression was strongly correlated with Il2, Il6, and Il10 expression." (PMID 23781124, 2013). "Consistent with this study, our results suggest that innate immune activation (here, IL-6) could offer a biological marker of the “urban influence” on systemic inflammation, and the development of asthma or other chronic disease." (PMID 22685596, 2012). "Several reports have demonstrated that TH2-type cytokines, including IL-4 and IL-13, enhance IL-17–induced release of IL-6 from fibroblasts, suggesting that IL-17 might be involved in asthma, which is a TH2-mediated disease." (PMID 22203879, 2012). "The suppression of all the symptoms of asthma in the present study was associated with reduced levels of various Th1 cytokines (TNF-α, IL-6, and IL-1β), with reduced levels of various Th2 cytokines (IL-4, IL-5 and IL13) and with reduced levels of a Th17 cytokines (IL-17F) in splenocytes." (PMID 23346203, 2012). "Interestingly, IL-17 is upregulated in asthma as eosinophils are cellular sources of its production, and IL-17 increases synthesis of IL-6 and IL-11 by bronchial fibroblasts derived from bronchial biopsies of asthmatic subjects." (PMID 22203879, 2012). "This study also examined whether the commonly used corticosteroid and β2 agonist combination therapy in the treatment of asthma could affect RV-induced IL-6 and RV replication." (PMID 22121382, 2011). "It has also been reported that astaxanthin significantly reduces the production of pro-inflammatory mediators and cytokines, namely nuclear factor-κB (NF-κB), tumour necrosis factor-α (TNF-α) and interleukin-6 (IL-6), and suppresses T lymphocyte activation in asthma patients." (PMID 21747748, 2011). "Indeed, hASMc are a source of chemokines and cytokines that play a role in chronic pulmonary diseases like COPD and asthma, including IL-8 and IL-6." (PMID 20875145, 2010). "The role of IL-6 in promoting effector T cell subsets suggest that IL-6 may play a functional role in asthma." (PMID 20205953, 2010). "IL-6 is therefore more than a proinflammatory marker in the lung and may play a role in the pathophysiology of asthma." (PMID 20205953, 2010). "Hierarchical regression analysis in the total study cohort indicates that the relationship between asthma and lung function could be mediated by IL-6." (PMID 20205953, 2010). "We then performed multiple regression analyses to explore whether IL-6 could be a mediator of the impaired lung function in asthma (Paths X and Y)." (PMID 20205953, 2010). "IL-6 levels are significantly increased in asymptomatic asthmatic patients compared to control patients, as well as during naturally occurring asthma attacks, indicating involvement of IL-6 in asthma pathogenesis." (PMID 20804555, 2010). "Future studies on the role of IL-6 in the pathophysiology of asthma are warranted and depending on the results from these studies, IL-6 could be a potential therapeutic target in this disease." (PMID 20205953, 2010). "IL-6 trans-signalling is critically involved in the maintenance of both asthma and colon cancer." (PMID 19174822, 2009). "This provides a further mechanism through which IL-6 and IgE contribute to the pathogenesis of asthma, and through which anti-IgE therapy might achieve its therapeutic effect." (PMID 18215266, 2008). "This study provides a further mechanism through which IL-6 and IgE contribute to the pathogenesis of asthma, and through which anti-IgE therapy might achieve its therapeutic effect." (PMID 18215266, 2008). "IL-6 is a complex and pleiotropic cytokine which has many functions and may contribute to the progression of asthma, since it polarizes T-helper cells towards a T-helper 2 phenotype." (PMID 16670028, 2006). "Obesity-related IL-6 activity may worsen lung function and increase asthma exacerbations." (PMID 41155381, 2025).
asthma (continued). "From the knowledge of the molecules involved in asthmatic inflammation, such as IL-6, it is possible to understand the pivotal role of severe asthma biological therapies both in terms of asthma and in relation to pathologies such as osteoporosis which correlate with asthma inflammation." (PMID 39857779, 2025). "Notably, perturbation in IL6 was associated with lower odds of atopic dermatitis and no elevation in odds of asthma." (PMID 40858837, 2025). "Circ_0005519 may increase IL-13/IL-6 level by adjusting let-7-a-5p to affect asthma." (PMID 38521909, 2024). "In addition, asthma is related to the airways’ persistent inflammation, and for example, tumor necrosis factor-α, IL-4, transforming growth factor-β, IL-6, and vascular endothelial cell growth factor are all involved in the inflammatory response of asthmatic lungs as well as airway remodeling." (PMID 38594768, 2024). "Thus, in contrast to the Type 2 (T2 or eosinophilic) type of asthma which was mediated by IL-4, IL-5, and IL-13, the profile of the inflammatory mediators with high levels of IL-6, CXCL8, and IFNγ after TLR stimulation mirrored that of the non-T2 endotype of asthma." (PMID 39614276, 2024). "The anti-inflammatory effects of the gut microbiota may be mediated by the endocannabinoid system, suggesting that modulation of the gut microbiota could reduce IL6 levels, thereby restoring immunity, reducing pulmonary inflammation, and alleviating asthma and COPD." (PMID 39654679, 2024). "Interestingly, IL6 is considered a potential biomarker for non-Th2 asthma in humans." (PMID 39594673, 2024). "Furthermore, IL-17 and IL-6 play an important role in Th2-low asthma and therefore a co-treatment with DCQAs might also be beneficial in reducing inflammation during this severe respiratory disease." (PMID 39239645, 2024). "IL-6 can also induce neutrophils to release soluble IL-6R which can act locally within the airway to activate eosinophils and act on airway epithelial cells to impair epithelial tight junction integrity and induce matrix metalloproteinases and the alarmin IL-33, contributing to pathology in asthma." (PMID 37180449, 2023). "Interestingly fibroblast-derived-IL-6 and IL-8 are critical proinflammatory cytokines that activate and attract neutrophils demonstrating an importance for eosinophil-fibroblast crosstalk for neutrophil-inflammation in asthma." (PMID 36911735, 2023). "However, most of these studies have small sample sizes, and a single study may lack sufficient statistical relevance to detect the potentially subtle effects of the IL-6 levels on asthma." (PMID 37173781, 2023). "Therefore, we sought to study the role of classic and trans IL-6 signaling in asthma in further detail and to use this information to develop an IL-6 gene signature that may be used to select potential patients for anti-IL-6 treatment." (PMID 38062491, 2023). "The underlying mechanisms of BA in the treatment of immune modulation on PF and asthma manifest as the regulation of Th17/Treg responses by promoting Treg cell differentiation, inhibiting the expression of Th17A, and reducing the levels of IL-6, IFN-γ, IL-4, and IL-23." (PMID 37007037, 2023). "Severe asthma refractory to biologic agents seems likely to be sustained by a significant slice of T2-low inflammation characterized by different T-cell effectors (T-helper 1 and T-helper 17) and specific cytokines (IL-17, IL-6, IL-8, interferon (IFN) and tumor necrosis factor (TNF))." (PMID 37189844, 2023). "Although a number of proinflammatory mediators may contribute to asthma per se, and may even be derived from fibroblasts, in pilot studies using a multiplex assay, we found IL-6, IL-8, CCL5 and TSLP to be particularly expressed, and importantly changed by TNFα treatment." (PMID 36760534, 2023). "Additionally, IL-6 is an important, asthma-involved cytokine." (PMID 36981614, 2023).
asthma (continued). "Besides IL-6, IL-1β is also among the factors inducing the differentiation of Th17 cells, which has also been shown to promote Th2 responses in murine models of asthma." (PMID 36233196, 2022). "The three subfamilies of MAPKs have been involved in the pathogenesis of asthma, and JNK and P-38, in particular, are more closely associated with asthmatic airway inflammation, which can cause high expression of downstream factors such as IL-6, IL-1β, and IL-4 and IL-5, respectively." (PMID 36081945, 2022). "In a murine model of asthma, exposure to NP (5 and 500 μg/kg bw∙day) in both bone-marrow derived dendritic cells (BM-DCs) and splenic classic dendritic cells CD11c(+) cDCs secreted increased levels of IL-6 and TNF-α, at both baseline and following lipopolysaccharide (LPS) stimulation." (PMID 35010832, 2022). "Also, Pro-inflammatory cytokines such as TNF-α, IL-1β, and IL-6 increase in asthma." (PMID 36076196, 2022). "Interestingly, IL6 increased asthma exacerbation risk in children but did not affect lung function or other severity indicators as in adults." (PMID 36140412, 2022). "IL6 promotes effector T cells, suggesting that it may have a functional role in asthma." (PMID 36140412, 2022). "IL-6 is a cytokine that regulates cell growth and differentiation, immune response and its expression was related to metabolic dysfunction and asthma severity, IL-9 orchestrate inflammation that takes place in asthma while IL2RB is involved in T cell-mediated immune responses." (PMID 36143090, 2022). "Finally, IL-6 was undetectable in approximately 70% of obese children with no asthma, in 57% obese asthmatic children and in 100% of children with normal-weight and asthma." (PMID 36291398, 2022). "This may explain the concomitant increase in IL-6 in patients with nocturnal asthma." (PMID 36505412, 2022). "In respiratory diseases and asthma, cytokines promote the survival of inflammatory cells, contributing to the maintenance of chronic inflammation and producing proinflammatory cytokines such as IL-1β, IL-6, and TNF-α, which are increased in the sputum and BALF of patients with asthma." (PMID 36555240, 2022). "Therefore, IL-6 may directly participate in the pathogenesis of asthma and increase the production of mucus in the lung airways." (PMID 33708257, 2021). "However, non-T2 asthma is a neutrophilic and paucigranulocytic heterogenous type, predominant in those with adult-onset and corticosteroid-resistant (less responsive), and inflammation-driven through IL-17, IL-6, and IL-23." (PMID 34566492, 2021). "It has been shown that patients with asymptomatic asthma may have higher blood IL-6 levels." (PMID 33503170, 2021). "The IL-6 signaling pathway in dendritic cells plays a critical role in the uptake of allergens and the initiation of Th2/Th17 mediated airway inflammation and airway hyperresponsiveness in asthma, thus providing a new potential target for the treatment of allergic asthma." (PMID 34402724, 2021). "IL-6 has been found associated with severe asthma in adults, but not in children." (PMID 33418879, 2021). "Therefore, we hypothesized that IL-6 may play a role in asthma disease through the regulation of ferroptosis." (PMID 34402724, 2021). "The exact pathogenic role of IL-6 in this phenotype of asthma has not yet been defined." (PMID 35055325, 2021). "Thus, following recruitment to the ASM, fibrocytes may retain the ability to contribute to monocyte‐mediated processes, as well as increasing levels of IL‐6, via interactions with ASM, both of which are implicated in asthma pathogenesis." (PMID 33209301, 2020). "These higher levels of IL-6 may contribute to driving CVD comorbidity in asthma." (PMID 32194407, 2020). "Interestingly, IL-6 can translocate from inflamed lung to the systemic circulation in mice, and was also found to be elevated in the sputum of some patients with mild to moderate asthma." (PMID 32194407, 2020).
asthma (continued). "Besides, IL-6/IL−6R is associated with TH17-differentiation and asthma severity." (PMID 31101830, 2019). "This suggests that IL-6 trans-signalling may have a key role in asthma severity." (PMID 31395050, 2019). "IL-6 is known for its capability to promote the differentiation of Th2 cells, inhibit Th1 and Treg differentiation and expansion in response to allergen, activate immunoglobulin class-switching in plasma cells and enhance the differentiation of Th17 cells, which are engaged in severe asthma." (PMID 30534125, 2018). "Moreover, IL-37b could significantly suppress the induced concentrations of Th2 and asthma-related cytokines IL-4, IL-6, and IL-13 in lung homogenate of asthmatic human PBMC NOD/SCID mice (all P < 0.05)." (PMID 29988381, 2018). "Interestingly, the healthy control subjects had significantly higher IL‐13 in their serum as compared to the severe asthmatics (P = .0002), whilst conversely, asthma patients had higher levels of IL‐6 and IL‐8 as compared to the healthy controls (both P < .0001)." (PMID 29130617, 2018). "Interestingly, we observed that treatment with systemic corticosteroids was associated with lower periostin levels, while those on montelukast had higher IL-6 in plasma, independently from the asthma severity and other potential confounders, including age, BMI, or co-morbidities." (PMID 28429138, 2017). "Moreover, information on other cytokines such as IL-6 or IL-1β which play an important role in the immunological pathways involved might provide a better understanding of the mechanisms related to asthma due to soybean and DEP." (PMID 28628664, 2017). "IL‐17F/IL‐6 axis might be involved in the pathophysiology of allergic airway inflammation, and targeting IL‐17F and its signaling pathways could be a novel strategy for asthma." (PMID 28474507, 2017). "Furthermore, increased levels of IL-6 and IL-8 have been reported in asthma patients." (PMID 24587090, 2014). "Also, omalizumab significantly reduced RNA and protein levels of IL-6, IL-8,TNFα and IL-4 in a dose-dependent manner in IgE-stimulated human airway smooth muscle cells isolated from biospsy specimens of patients with asthma, chronic obstructive pulmonary disease and healthy controls." (PMID 24004581, 2013). "Moreover, an increase in the airway hyperresponsiveness of asthma and airway remodeling may be due to increased production of IL-4, IL-5, IL-6, and IL-13 in the inflammated airways." (PMID 23533467, 2013). "A recent study showed that the only biomarkers that could distinguish severe or moderate asthma from mild asthma are neutrophil count and IL-8, out of the eight potential biomarkers (IL-8, neutrophils, eosinophils, IL-1Rα, IL-1α, IL-5, IL-6, and RANTES) investigated in BALF." (PMID 23355837, 2013). "In order to investigate whether IL-6 might be more than an inflammatory marker in asthma, we determined the levels of IL-6, TNFα and IL-1β in induced sputum and then related this to lung function in a group of mild-moderate allergic asthmatic and healthy control subjects." (PMID 20205953, 2010). "Thus, IL-6 can contribute to increase airway obstruction in asthma." (PMID 20205953, 2010). "Moreover, there has been relatively less interest in the pathobiology of IL-6 in human asthma." (PMID 20205953, 2010). "The increased risk has been estimated to be 1.5-3.0-fold compared to healthy non-smokers without asthma, while some studies have reported synergy of asthma with female gender, atopy, or polymorphisms in the interleukin (IL)-6 gene towards increasing lung cancer risk." (PMID 20796309, 2010). "Therefore, clarifying the effect of IL-6 in balancing between functions of Th17 cells and regulatory T cells during allergic responses will make it more clear that blockade of IL-6 is effective for the inhibition of Th17 cell-mediated inflammation in asthma." (PMID 20565710, 2010).